RNU6-1026P (RNA, U6 small nuclear 1026, pseudogene)
Gene: Small nuclear RNA gene on chromosome 1 (50,582,404 to 50,582,511, forward strand). Ensembl gene ENSG00000207194.
Homologues: Orthologues: chimpanzee U6 (99% identical), macaque U6 (92% identical). Paralogues in human: RNU6-116P (89% identical), RNU6-38P (89% identical), RNU6-25P (88% identical), RNU6-29P (88% identical), RNU6-33P (88% identical), RNU6-39P (88% identical), RNU6-46P (88% identical), RNU6-476P (88% identical), RNU6-480P (88% identical), RNU6-698P (88% identical), RNU6-1 (87% identical), RNU6-1031P (87% identical), and 1287 more.